TNF (tumor necrosis factor)
Diseases named in the same sentence as TNF in open-access papers (continued):
Sharing a sentence is not in itself a finding about the gene and the disease.
rheumatoid arthritis (continued). "Since the advent of etanercept, the first TNF-inhibitor approved for use in rheumatoid arthritis (RA), there has been a proliferation of biologics exploiting different molecular targets." (PMID 36550585, 2022). "A previous study confirmed the implication of inflammatory cytokines, TNF and IL-1, in the progression of rheumatoid arthritis and osteoarthritis." (PMID 35734177, 2022). "For example, exosomes released from the synovial fibroblasts of patients with rheumatoid arthritis have high concentrations of membrane-bound TNF-α, which exacerbates the pathology of rheumatoid arthritis." (PMID 35628473, 2022). "We describe the case of a 68-year-old man with rheumatoid arthritis and tumor necrosis factor alpha (TNF-α) inhibitor treatment-related immunodeficiency, who suffered from disseminated histoplasmosis after traveling to Brazil." (PMID 36104715, 2022). "The TNF-α pathway is an important therapeutic target for autoimmune diseases, such as rheumatoid arthritis, psoriasis, seronegative spondyloarthropathies, and inflammatory bowel disease." (PMID 36505429, 2022). "The KEGG analysis of these hub genes was also enriched in many immune and inflammatory pathways, including cytokine-cytokine receptor interaction, rheumatoid arthritis, chemokine signaling pathway, TNF signaling pathway." (PMID 36387896, 2022). "Current therapies for rheumatoid arthritis include methotrexate (first-line drug), glucocorticoids, tumor necrosis factor α (TNFα) inhibitors, and Janus kinase inhibitors." (PMID 36142208, 2022). "lncRNA-mRNA ChIP analysis uncovered the action of Caulophyllum robustum Maxim, which can play a part in rheumatoid arthritis via lncRNA-mediated signing pathways, including tumor necrosis factor, chemokine, and Toll-like receptor signaling pathways." (PMID 36014574, 2022). "It was reported that NIC has a therapeutic effect on rheumatoid arthritis by reducing TNF-α-induced cytokine expression and release in synovial cells of human fibroids with rheumatoid arthritis." (PMID 36555754, 2022). "Synovial fibroblasts are affected by rheumatoid arthritis, and the cytokine TNF upregulates TRPA1, the activation of which can increase the intracellular calcium level, leading to lactate dehydrogenase release." (PMID 36278189, 2022). "For example, combination of anti-IL1 and TNFα provides synergistic effect on the treatment of rheumatoid arthritis." (PMID 36668761, 2022). "The effect of anti-TNF medication versus non-TNF therapy (biologics and small targeted compounds) on weight gain in patients with rheumatoid arthritis are compared." (PMID 35784983, 2022). "Since inflammatory cytokines, such as TNF-α, are usually increased in rheumatoid arthritis, we further addressed the effect of rIFNγ on TNF-α-induced osteoclast formation." (PMID 36148242, 2022). "IL-33 is also a crucial regulator of inflammation in rheumatoid arthritis patients and mouse models alike, wherein it activates TNF pathways in fibroblasts." (PMID 35439171, 2022). "For example, exosomes released from synovial fibroblasts of patients with rheumatoid arthritis accumulate high concentrations of membrane-bound TNF-α, exacerbating the pathology of rheumatoid arthritis." (PMID 36298556, 2022). "Anti-TNF therapies are a core anti-inflammatory approach for chronic diseases such as rheumatoid arthritis and Crohn’s Disease." (PMID 35027468, 2022). "Infliximab is a monoclonal antibody to human tumor necrosis factor alpha, a drug commonly used in severe inflammatory bowel disease, rheumatoid arthritis, among other diseases." (PMID 35273881, 2022). "This is in line with the reported anti-inflammatory effect of RSV decreasing TNF-α in diabetic nephropathy, LPS-induced cardiac injury and rheumatoid arthritis animal models." (PMID 35334601, 2022). "Up to 500-fold increases in bivalent anti-TNF sdAbs (VHH) were reported with rheumatoid arthritis treatment in vivo, compared to monovalent molecules." (PMID 36044435, 2022).
rheumatoid arthritis (continued). "KEGG pathway analysis indicates that the genes were significantly enriched in Cytokine-cytokine receptor interaction, IL-17 signaling pathway, Rheumatoid arthritis and TNF signaling pathway." (PMID 36118873, 2022). "On the other hand, peripheral mononuclear cells from patients with rheumatoid arthritis and cultured in the presence of vitamin D had reduced levels of IL-17, IL-6, and TNF-α." (PMID 35625788, 2022). "The exact cause of rheumatoid arthritis (RA) is unknown, but inflammatory mediators such as TNF-α, IL-1β, COX-2, and nitric oxide (NO) are responsible for the destruction of articular cartilage." (PMID 35268651, 2022). "A variety of TNF-α blockers have been used for autoimmune diseases, such as rheumatoid arthritis, inflammatory bowel disease, and multiple sclerosis." (PMID 36505429, 2022). "TNF-α stimulates various cells by binding to its specific receptors on the cells to promote several pathological pathways, such as those involved in rheumatoid arthritis, psoriasis, and cancer." (PMID 36204127, 2022). "Activation of MAPK members was increased in macrophages and fibroblasts in the synovial tissue of patients with rheumatoid arthritis, which coincided with increased IL-6, TNF-α, and IL-1 stimulation in synovial fibroblast cells." (PMID 35755835, 2022). "Our previous studies documented some associations between polymorphisms in the genes encoding Th2 cytokines and response to anti-TNF therapy as well as clinical parameters of patients diagnosed with AS and other rheumatic diseases such as rheumatoid arthritis (RA) or psoriatic arthritis (PsA)." (PMID 36361964, 2022). "Systemic lupus erythematosus (SLE) induced by biologics mostly occurs during the treatment of psoriasis with tumor necrosis factor-alpha (TNF-α) inhibitors, especially in patients with psoriatic and rheumatoid arthritis." (PMID 35733860, 2022). "Recruitment of osteoclasts induced by TNF-α is central to the inflammatory element of destructive bone diseases, and TNF-α-targeted drugs are a known effective tool for suppressing inflammatory bone destruction in diseases such as rheumatoid arthritis." (PMID 35163403, 2022). "It is well established that dysregulated TNF production is detrimental in various autoimmune diseases including rheumatoid arthritis, psoriasis and IBD." (PMID 34054827, 2021). "Based on determination of the amount of TNF-α in the peripheral blood, it is possible to assess the severity of the course of rheumatoid arthritis." (PMID 33498456, 2021). "The actual incidence of DIIP was 1.0% of total patients in this study, which was similar to the incidence of DIIP by humanized biologics targeting TNF-alpha (0.5%) in Japanese postmarketing surveillance for Rheumatoid Arthritis." (PMID 33411857, 2021). "Biologics targeting tumor necrosis factor, which plays a central role in the inflammatory process, and Janus kinase inhibitors have been introduced in the treatment of rheumatoid arthritis, making clinical remission a realistic treatment goal." (PMID 33802804, 2021). "The reporter assay was run under standard conditions (10 pM hTNF) and at 100 pM hTNF (significantly higher than the sub-10 pM levels of TNF present in the synovium of rheumatoid arthritis patients)." (PMID 33495441, 2021). "cross-sectional multicenter study including rheumatoid arthritis patients who were initiated the first biological treatment either: Rituximab, an anti-TNF, or Tocilizumab." (PMID 33995789, 2021). "IL-6 and TNF-α have important roles in the early- and late-stage pathogenesis of rheumatoid arthritis." (PMID 34064515, 2021). "Both TNF-α and interleukin-1 (IL-1) play major role in pathogenesis of inflammatory disorders such as rheumatoid arthritis." (PMID 33945040, 2021). "In our study, we found out that Fuzi can target proinflammatory cytokines associated genes including TNF and IL6 to ameliorate rheumatoid arthritis." (PMID 34845218, 2021).
rheumatoid arthritis (continued). "TNF-α has previously been shown to be involved in the development of both rheumatoid arthritis and type 1 diabetes." (PMID 34878845, 2021). "TNF-α has been validated as a key mediator of inflammation for the success of anti-TNF-α treatment in rheumatoid arthritis, Crohn's Disease and other related chronic inflammatory conditions." (PMID 33897879, 2021). "In spite of possible side effects, TNF neutralization is a golden standard in treating rheumatoid arthritis, psoriasis and inflammatory bowel disease therapy." (PMID 34084159, 2021). "Tumor necrosis factor (TNF) is a regulator of several chronic inflammatory diseases, such as rheumatoid arthritis." (PMID 34638561, 2021). "This radiotracer is based on a TNF inhibitor, namely the certolizumab pegol (CZP); it is a PEGylated humanized Fab fragment anti-TNF approved for the treatment of different immune diseases such as rheumatoid arthritis and Crohn disease." (PMID 34298967, 2021). "Analysis of the IL-33 genotypes distributions with regard to therapeutic response to anti-TNF agents in rheumatoid arthritis, ankylosing spondylitis and psoriatic arthritis patients." (PMID 34177886, 2021). "Some studies have found that the use of TNF-α inhibitors in patients with rheumatoid arthritis reduces inflammation and coagulation markers, as well as decreases the inhibition of fibrinolysis and the incidence of VTE18,19." (PMID 34426637, 2021). "One large clinical study compared the effects of tofacitinib citrate on diabetes worsening to other commonly used treatments for rheumatoid arthritis, namely abatacept, a TNF inhibitor (TNFi), rituximab, and tocilizumab." (PMID 34769307, 2021). "Mouse-human chimeric tumor necrosis factor-alpha (TNFα) blocking molecular antibody (cA2, infliximab) is used to treat inflammatory conditions, like Crohn’s disease and rheumatoid arthritis." (PMID 34356857, 2021). "The group proposed beneficial effects of vagal stimulation in situations where high levels of tumor necrosis factor alpha (TNF α) promote clinical symptoms, e.g. inflammatory bowel diseases, rheumatoid arthritis and abdominal sepsis." (PMID 34376743, 2021). "Ablation of ADAM17 in myeloid cells is protective against rheumatoid arthritis to a similar extent as the ablation of TNF." (PMID 33579029, 2021). "Biologics targeting proteins such as TNFα for rheumatoid arthritis and IL-17 for psoriasis are prime examples of how knowledge about key nodal points mediating disease mechanisms can lead to therapies that change treatment paradigms for patients." (PMID 34803999, 2021). "Circulating levels of TNF-α are altered in many pathologies that exhibit sleep disturbances, including chronic inflammation, rheumatoid arthritis, insomnia, and chronic fatigue syndrome." (PMID 34943452, 2021). "The most significantly enriched pathway within the differential expression dataset for adalimumab good-responders was in ‘B and T cell signalling in rheumatoid arthritis’ (p = 1.4E− 10) with TNF identified as one of the top upstream regulators (p = 1.53E− 06)." (PMID 33691749, 2021). "Etanercept is the anti-tumor necrosis factor (TNF) therapeutic protein approved for the treatment of rheumatoid arthritis." (PMID 32766842, 2021). "We aimed to validate the association of 28 GWAS-identified genetic variants for response to TNF inhibitors (TNFi) in a discovery cohort of 1361 rheumatoid arthritis (RA) patients monitored in routine care and ascertained through the REPAIR consortium and DANBIO registry." (PMID 34777329, 2021). "Fortunately, IL-6 and TNF-α have recently been shown to regulate miR-34a transcription and participate in rheumatoid arthritis." (PMID 34504639, 2021). "In several autoimmune diseases identification and subsequent blockade of specific cytokines has led to successful therapies, for example tumor necrosis factor-alpha (TNF-α) inhibition in rheumatoid arthritis." (PMID 34768756, 2021).
rheumatoid arthritis (continued). "The present meta-analysis was an effort to assess the various adverse effects after anti-TNF α therapy to treat rheumatoid arthritis, psoriatic arthritis, and ankylosing spondylitis." (PMID 34790122, 2021). "In rheumatoid arthritis patients, a significant decrease in serum chemerin was observed following anti-TNF therapy." (PMID 34640632, 2021). "TNFα inhibitors (TNFis) have emerged as one of the most effective classes of drugs for inflammatory arthritis, including rheumatoid arthritis, psoriatic arthritis, and ankylosing spondylitis." (PMID 34301319, 2021). "Inflammatory mediators (e.g., TNF-α) are critical elements of pathological conditions observed in periodontitis, age-related osteoporosis, and rheumatoid arthritis." (PMID 33765924, 2021). "It is well accepted that macrophages play an essential role in the pathogenesis of inflammatory disease rheumatoid arthritis (RA) by producing pro-inflammatory cytokines like TNF-α, IL-1β, IL-6 that can drive osteoclastogenesis and bone destruction." (PMID 34421899, 2021). "Biologic drugs, especially anti-TNF, are considered as the gold standard therapy in rheumatoid arthritis." (PMID 33679801, 2021). "TNFα-neutralizing antibodies have shown good effects in multiple auto-immune chronic inflammatory condition including rheumatoid arthritis, Crohn’s disease and psoriasis." (PMID 34098956, 2021). "Abnormal production of TNF-α and TNF receptor signaling has been associated with the pathogenesis of several inflammatory diseases including rheumatoid arthritis, Crohn’s disease, atherosclerosis, psoriasis, and cancer." (PMID 33986746, 2021). "In the rheumatoid arthritis synovial fibroblasts (RASFs) of human, the expression level of cPLA2 is increased by proinflammatory cytokines such as TNF-α and IL-1β." (PMID 33796022, 2021). "Rheumatoid arthritis (RA) is a chronic autoimmune disease characterized by joint destruction; cytokines such as tumor necrosis factor-α (TNF-α) and interleukin-6 (IL-6) play key roles in systemic inflammation." (PMID 33658620, 2021). "EXO purified from synovial fibroblast of rheumatoid arthritis patients contain TNF-α at the transmembrane domain that induce NF-κB activation and MMP-1 release in acceptor / by stander cells." (PMID 34208697, 2021). "Blocking of the Tumor Necrosis Factor (TNF) activity is a successful therapeutic approach for 50–60% of rheumatoid arthritis (RA) patients." (PMID 33882889, 2021). "Tumor necrosis factor α inhibitors (TNFi) is effective for rheumatoid arthritis (RA) patients who fail to conventional synthetic disease-modifying anti-rheumatic drugs (csDMARDs)." (PMID 33663487, 2021). "Local and systemic inflammation in patients with rheumatoid arthritis was effectively reduced by blocking TNF-α." (PMID 35049883, 2021). "The Anti-TNF Trial in Rheumatoid Arthritis with Combination Therapy (ATTRACT) trial concluded that the frequency of serious infections was comparable between those that received MTX/infliximab and those treated with MTX38." (PMID 34790122, 2021). "Vitamin B-6 has also been associated with inflammation (CRP) in the NHANES study (2003-2004), and B-6 supplementation in rheumatoid arthritis patients has been shown to reduce levels of IL-6 and TNF-α." (PMID 34836049, 2021). "One-third of patients with rheumatoid arthritis (RA) display an inadequate primary response to anti-tumor necrosis factor (TNF)-based drugs." (PMID 33477865, 2021). "TNF-alpha inhibitors are remarkable in treating inflammatory bowel disease and rheumatological conditions including rheumatoid arthritis and ankylosing spondylitis." (PMID 34804701, 2021). "It has been shown that TNFR1 knock down effectively inhibited TNFα-induced cytokine production in rheumatoid arthritis." (PMID 34093519, 2021). "IL-37 has an anti-inflammatory effect in rheumatoid arthritis, reduces the secretion of IL-1β, IL-6, and TNF-α and MIP-2, and mediates M2 macrophage polarization." (PMID 34842603, 2021).
rheumatoid arthritis (continued). "Anti-TNF-α therapy in rheumatoid arthritis patients decreases brain-derived TNF-α and alleviates pain." (PMID 34512420, 2021). "Therapeutic blockade of TNF-α has been proposed in different inflammatory-related conditions, including rheumatoid arthritis and inflammatory bowel disease." (PMID 34683379, 2021). "Nevertheless, the investigation of pathogenic cytokines (such as TNF) has led to the development of anti-TNF therapy for patients with debilitating chronic inflammatory diseases, such as rheumatoid arthritis." (PMID 34571869, 2021). "In our study, we synthesized an 11-mer phosphorothioate ASO aimed at inhibiting TNF-α and compared its effects on the dynamics of the course of rheumatoid arthritis in rats to the effects of adalimumab." (PMID 33498456, 2021). "Although TNF-α was identified as promising cancer therapeutic and several agonists were developed for that purpose, TNF-α antagonists have a greater value in treating inflammatory and autoimmune diseases (rheumatoid arthritis)." (PMID 33801589, 2021). "FcγRIIb inhibition promotes the overproduction of pro-inflammatory cytokines, including TNF-α which is active in inflammatory diseases, including Grave’s disease, rheumatoid arthritis, periodontitis and SLE." (PMID 33861790, 2021). "The results of KEGG enrichment revealed the involvement of several major pathways, including those related to cytokine–cytokine receptor interaction, osteoclast differentiation, rheumatoid arthritis, and NF-κB and TNF signaling pathways." (PMID 34803714, 2021). "The influence of treatment of rheumatoid arthritis with infliximab (anti-TNF-α) on comorbid PD has been examined." (PMID 34208697, 2021). "Kavanaugh A, St Clair EW, McCune WJ, Braakman T, Lipsky P. Chimeric anti-tumor necrosis factor-alpha monoclonal antibody treatment of patients with rheumatoid arthritis receiving methotrexate therapy." (PMID 33909773, 2021). "In summary, using TNF-Tg mice as a model of chronic inflammatory arthritis, we reported for the first time that NG-R1 promoted lymphatic drainage function to ameliorate rheumatoid arthritis by suppressing the NF-κB signaling pathway." (PMID 35280253, 2021). "It has been shown that TNF inhibition increases serum PTH levels in patients with rheumatoid arthritis." (PMID 33861790, 2021). "In another study with endothelial cells from patients with rheumatoid arthritis (RA), IL-17 (in combination with TNF-α) induced a procoagulant and prothrombotic phenotype (beyond the inflammatory state)." (PMID 34540858, 2021). "We found the maximum tolerated dose of seliciclib, an orally available CDK inhibitor, in a phase 1b trial among patients with rheumatoid arthritis refractory to TNF blockade, further evaluating the safety and tolerability of the intervention." (PMID 33928262, 2021). "In rheumatoid arthritis, tumor necrosis factor-α (TNF-α) plays a role in the release of cytokines and thus causes chronic inflammation." (PMID 34451803, 2021). "Currently, Baricitinib is FDA-approved (at 2 mg daily dose) for rheumatoid arthritis (RA) patients failing Tumor Necrosis Factor (TNF) inhibitors." (PMID 34680353, 2021). "These therapies inhibit the proinflammatory action of TNF-α in common autoimmune diseases such as rheumatoid arthritis, psoriasis, ulcerative colitis, and Crohn’s disease." (PMID 33854514, 2021). "Adalimumab, as a TNF inhibitor biologic for the treatment of rheumatoid arthritis, is one of the top-selling drugs worldwide." (PMID 33889152, 2021). "This study identified a maximum tolerated dose of 400 mg seliciclib in patients with active rheumatoid arthritis refractory to anti-TNF therapy, either as monotherapy or with background conventional synthetic DMARDs." (PMID 33928262, 2021). "Cluster #3 mainly related to certolizumab pegol, a tumor necrosis factor blocker, can be used for the treatment of rheumatoid arthritis, Crohn's disease, psoriatic arthritis, and axial spondyloarthritis." (PMID 33941172, 2021).